CXCR1 (C-X-C motif chemokine receptor 1)
Diseases named in the same sentence as CXCR1 in open-access papers (continued):
Sharing a sentence is not in itself a finding about the gene and the disease.
Obesity (8 papers, 2016 to 2025). Accumulation of substantial excess body fat. "A mouse model of diet-induced obese (DIO) has suggested that obesity-induced secretion of CXCL1 by cancer cells creates a chemotactic gradient that enables ADSCs trafficking to tumors via CXCR1." (PMID 31861872, 2019). "Together, these results indicate that CXCL1 signalling via CXCR1 and CXCR2 mediates the obesity-associated stimulation of tumour growth." (PMID 27241286, 2016). "The emerging evidence on the potential relevance of CXCR1/2 signaling in the onset and progression of obesity-driven metabolic diseases and related complications is investigated in phase 2 clinical studies in obese Type 2 Diabetes (started at December 2020, EudraCT Nr." (PMID 34571976, 2021). "To assess whether ASCs could be recruited in response to CXCL1 secreted by tumours in obesity, we performed immunofluorescence analysis of CXCR1 and CXCR2, the receptors of CXCL1 and CXCL8." (PMID 27241286, 2016). "Our results suggest that the obesity-associated CXCL1 expression by prostate epithelium could be responsible for recruitment of ASCs, the WAT stromal cells expressing CXCR1." (PMID 27241286, 2016). "Indeed, the role of the CXCR2 pathway in obesity-induced inflammatory response was confirmed by the observation that a CXCR1/2 inhibitor was effective in the db/db mouse model in reducing neutrophil and macrophage infiltration in the liver and in the adipose tissue." (PMID 34571976, 2021). "Human and animal studies have shown CXCR1/2 agonists (e.g., CXCL8, CXCL5 in T1D patients, CXCL1 in mice) to be correlated with obesity and insulin resistance." (PMID 40718478, 2025). "Another possibility being the dependence of neutrophil chemotaxis on CXCL5 (LIX), binding both CXCR1 and CXCR2, which levels are also increased in obesity." (PMID 33673387, 2021). "Primary examples include chemokine receptors (CXCR1, CXCR2, CXCR4, CCR5, CCR7) that drive chronic inflammatory responses common to both obesity and cancer." (PMID 33329395, 2020). "Combined, our results suggest that in patients, CXCR1 expressed in ASCs in vivo, and possibly CXCR2, direct ASC trafficking towards CXCL8 gradient activated in cancer and CXCL1 gradient in addition activated in obesity." (PMID 27241286, 2016).
pyelonephritis (8 papers, 2009 to 2025). An inflammatory process affecting the kidney. "We examined 5 polymorphisms in CXCR1, as previous studies have described an association of 2 polymorphisms with an increased risk of pyelonephritis in children." (PMID 20016852, 2009). "Moreover, polymorphisms in IL8 and its receptor CXCR1 are associated with an increased risk of pyelonephritis." (PMID 40701780, 2025). "Research shows that in children prone to pyelonephritis, CXCR1 expression in neutrophils is lower than in age - matched controls, suggesting susceptibility to pyelonephritis may be related to impaired neutrophil recruitment ability." (PMID 40308964, 2025). "Two separate studies reported associations of CXCR1 variants with pyelonephritis." (PMID 19543401, 2009). "Work in humans has identified genetic factors that confer susceptibility to pyelonephritis and renal scarring, including polymorphisms reducing IRF3 or CXCR1 (encoding IL-8 receptor) expression, in certain UTI-prone kindreds." (PMID 33513212, 2021). "Reduced expression levels of CXCR1 and TLR4 in neutrophils are associated with pyelonephritis, recurrent cystitis, and asymptomatic bacteriuria in children and premenopausal women." (PMID 21151974, 2010). "In addition, reduced expression levels of CXCR1, CXCR2 and TLR4 on neutrophils was associated with pyelonephritis, recurrent cystitis and asymptomatic bacteriuria, respectively." (PMID 19543401, 2009). "In addition, reduced expression levels of CXCR1 and CXCR2 on neutrophils was associated with pyelonephritis and recurrent cystitis, respectively." (PMID 20016852, 2009). "Susceptibility to rUTI and/or pyelonephritis in humans is associated with polymorphisms in the genes for non-secretor blood group antigens, P1 phenotype, CXCR1, TLR1, TLR2, TLR4, and TLR5." (PMID 20016852, 2009). "Children prone to pyelonephritis and recurrent UTI exhibit lower expression of CXCR1 compared with age-matched controls." (PMID 40701780, 2025). "The chemokine receptors CXCR1 and CXCR2, highly expressed on neutrophil surfaces, enable their recruitment to kidney infection sites by CXCL1 and CXCL." (PMID 40308964, 2025). "In this study, we examined whether CXCR1, CXCR2, and TLR pathway polymorphisms are associated with ASB, urinary chemokines, and neutrophils in a cross-sectional study of adult women ages 18–49 years with and without a history of recurrent cystitis or pyelonephritis." (PMID 20016852, 2009).
breast tumor (7 papers, 2012 to 2022). "Immunohistochemistry was employed to assess the expression of CXCR1 and BQ in the primary ER+ve breast tumor." (PMID 35054486, 2022). "When analyzing race category within the luminal B subtype, we found that CXCR1 was lower in Asian versus White breast tumors." (PMID 35754051, 2022). "Ginestier and colleagues also showed that blocking of both the receptors for IL8, CXCR1, and CXCR2, by treatment with the drug repertaxin, significantly reduced the formation of bone metastasis after intracardiac injection of breast tumor cells in mice." (PMID 23113900, 2012).
chronic obstructive pulmonary disease (7 papers, 2011 to 2025). A chronic and progressive lung disorder characterized by the loss of elasticity of the bronchial tree and the air sacs, destruction of the air sacs wall, thickening of the bronchial wall, and mucous accumulation in the bronchial tree. "Several CXCR1/2 inhibitors are now undergoing clinical trials for cystic fibrosis, chronic obstructive pulmonary disease (COPD) and ulcerative colitis." (PMID 38375330, 2024). "The selective CXCR1 antagonist navarixin was originally developed for treatment of chronic obstructive pulmonary disease (COPD), asthma and psoriasis." (PMID 37114134, 2023). "However, another study using SCH527123 (MK-7123, Navarixin), a CXCR1/2 antagonist, was also attempted in chronic obstructive pulmonary disease (COPD) but was abandoned because of a severe decline in neutrophil number." (PMID 32848733, 2020).
cystic fibrosis (7 papers, 2011 to 2024). Autosomal recessive disorder caused by pathogenic variants in the CFTR gene (cystic fibrosis transmembrane conductance regulator), which encodes a chloride and bicarbonate channel expressed in epithelial cells, and follow the diagnosis criteria. "Similar to cystic fibrosis, CXCL8 is associated with induction of bronchoconstriction by stimulation of CXCR1/CXCR2-expressing airway smooth muscle cells, as shown in guinea pigs." (PMID 36725964, 2023). "Finally, in a fascinating response to bacterial infection, proteases in the airways of cystic fibrosis patients were found to cleave CXCR1 expressed on neutrophils, releasing glycosylated CXCR1 peptides." (PMID 28178200, 2017). "An argument is that CXCR1 is redundant; however the importance of CXCR1 was highlighted by studies suggesting that CXCR1 plays a significant role on the regulation and progression of chronic inflammatory disorders, including cystic fibrosis, COPD, and in sporadic urinary infections." (PMID 22174759, 2011). "The role for IL-8 in CXCR1/CXCR2-mediated neutrophil recruitment in chronic airway inflammatory diseases, including COPD and cystic fibrosis, has been delineated." (PMID 22936990, 2012).
head and neck squamous cell carcinoma (7 papers, 2012 to 2024). A squamous cell carcinoma that arises from any of the following anatomic sites: lip and oral cavity, nasal cavity, paranasal sinuses, pharynx, larynx, and salivary glands. "The chemokine receptors CXCR1/2 play a key role in the aggressiveness of several types of cancers including head and neck squamous cell carcinomas (HNSCCs)." (PMID 34430714, 2021). "In head and neck squamous cell carcinoma (HNSCC), the infiltration numbers of CXCR1/2+CD15+ PMN-MDSCs and CD14+ M-MDSCs with immunosuppressive function are significantly increased." (PMID 36131911, 2022). "IL-8 (CXCL-8) is a member of the CXC chemokines family and IL-8 receptors CXCR1 and CXCR2 are expressed on various normal and cancerous cells including head and neck squamous cell carcinoma." (PMID 22507529, 2012). "We have identified an additional phase I/II trial treating patients with metastatic TNBC or p16-negative head and neck squamous cell carcinoma (HNSCC) with bintrafusp alfa, the cancer vaccine MVA-BN-CV301/FPV-CV301, and SX-682, a small molecule inhibitor of CXCR1/2 (NCT04574583)." (PMID 34063388, 2021).
type 1 diabetes (7 papers, 2015 to 2025). "Mouse Cxcr1 and Cxcr2 genes are located in an insulin-dependent diabetes genetic susceptibility locus." (PMID 26230114, 2015). "In type 1 diabetes patients with transplanted pancreatic islets, elevated circulating CXCL8 levels are detected, and CXCR1/CXCR2 activation has been associated with mediating damage to and reducing survival of these islets." (PMID 36725964, 2023). "Nevertheless, in view of recently-published experimental data obtained in NOD mice, we argue for possible Cxcr1 involvement in type 1 diabetes pathogenesis." (PMID 26230114, 2015). "The relationship between the KC/CXCR1/2 axis and the development of insulitis and type 1 diabetes in mice has been previously established, demonstrating that transient CXCR1/2 inhibition by ladarixin prevents inflammation-mediated islet damage in multiple low-dose streptozotocin mice." (PMID 34571976, 2021). "In another murine model, a CXCR1/CXCR2 antagonist prevented and reversed also type 1 diabetes, for which clinical trials are currently ongoing (vide infra)." (PMID 36725964, 2023). "As neutrophil migration into inflammatory sites can be prevented by targeting CXCR1 and CXCR2 receptors, we recently tested whether blocking these chemokine receptors by an allosteric inhibitor (ladarixin, LDX) was able to modify the development of type 1 diabetes." (PMID 37409229, 2023). "Deciphering whether correlation of low Cxcr1 expression with type 1 diabetes in mouse is involved in disease pathogenesis still requires further experiments such as proving Cxcr1 protein expression in healthy pancreatic islets or analyzing the consequences of Cxcr1 gene deletion in NOR mice." (PMID 26230114, 2015).
acute pyelonephritis (6 papers, 2007 to 2021). "Genetic factors involved in host susceptibility to acute pyelonephritis have been described including polymorphisms that reduce expression of the interferon regulatory factor 3 (IRF3) or CXCR1 coding for the IL-8 receptor." (PMID 31284699, 2019). "CXCR1 mRNA and protein expression was found to be reduced on acute pyelonephritis prone patient-neutrophils in association with polymorphisms in CXCR1 gene." (PMID 26230114, 2015). "Defects in expression of IL-8 receptors CXCR1 and CXCR2 have been associated with many infectious diseases, particularly acute pyelonephritis." (PMID 21151974, 2010). "The IL-8 receptor, CXCR1, was identified as a candidate gene when mIL-8Rh mutant mice developed acute pyelonephritis (APN) with severe tissue damage." (PMID 17786197, 2007). "The percentage of CXCR1 expression in healthy controls, chronic UTI patients, and acute pyelonephritis patients was 96±1.75, 97±2.4 and 97±1.7%, respectively." (PMID 21151974, 2010).
colitis (6 papers, 2018 to 2025). Inflammation of the colon. "The pharmacological evaluation showed that FMPs attenuated inflammation in AA-induced colitis by reducing the serum concentrations of TNF-α, IL-6, IL-8, and IL-10 and the colonic concentrations of MPO, MMP9, and CXCR1." (PMID 35620404, 2022). "At present, there is no valid evidence of the relationship between CXCR1/2 signaling and NET release in active colitis." (PMID 39328405, 2024).
non-small cell lung carcinoma (6 papers, 2015 to 2024). A group of at least three distinct histological types of lung cancer, including non-small cell squamous cell carcinoma, adenocarcinoma, and large cell carcinoma. "The contribution of ELR-CXC chemokines such as CXCL8/IL-8 and its receptors CXCR1/2 to cancer progression, including non-small cell lung cancer, has been well-documented." (PMID 26087179, 2015). "Our findings collectively suggest that G31P, via targeting CXCR1/2 signaling, can be considered as an important factor in therapeutic strategies designed for the clinical management of non-small cell lung cancer." (PMID 26087179, 2015). "We examined mRNA levels of CXCR1 and CXCR2 in a panel of non-small cell lung cancer cell lines including A549, H460, H358, H1299, and H322." (PMID 26087179, 2015).
pneumonia (6 papers, 2017 to 2025). An acute, acute and chronic, or chronic inflammation focally or diffusely affecting the lung parenchyma, caused by an infection in one or both of the lungs (by bacteria, viruses, fungi, or mycoplasma.). "Flow cytometry analysis showed that CXCR1 expression was significantly upregulated in the lung DCs of pneumonia patients." (PMID 40789072, 2025). "The expression of CXCR1/2 was further examined by immunohistochemical staining of pneumonia samples." (PMID 31988368, 2020). "However, the CXCR1/2 proteins were detected in neutrophils, which infiltrated in the lung in pneumonia." (PMID 31988368, 2020). "Therefore, we concluded that the expression of CXCR1/2 in pneumonia was positively correlated with the number of neutrophil infiltrated in the lung." (PMID 31988368, 2020). "Immunohistochemical results showed that CXCR1/2 were expressed in neutrophil in pneumonia." (PMID 31988368, 2020). "Both CXCR1 and CXCR2 expression were up-regulated in all pneumonia samples." (PMID 31988368, 2020).
ulcerative colitis (6 papers, 2015 to 2025). An inflammatory bowel disease involving the mucosal surface of the large intestine and rectum. "Evidence from the model implicated the involvement of CXCL8 and its receptor CXCR1 in the progression of ulcerative colitis." (PMID 41427018, 2025). "In ulcerative colitis (UC), increased epithelial CXCR1 protein expression was found and a meta-analysis afterwards identified CXCR1 and CXCR2 as additional UC risk loci." (PMID 26230114, 2015). "Blockage of CXCR1 by repertaxin, CXCR inhibitor, significantly diminished clinical symptoms of inflammation, thus being a potential therapeutic approach for ulcerative colitis." (PMID 41427018, 2025). "Numerous studies showed that the expression of CXCR1 and/or CXCR2 increased in many inflammatory disease, such as ulcerative colitis and hyperoxia-induced lung injury, so that massive neutrophils could be recruited into the site of inflammation." (PMID 31988368, 2020).
Arthritis (5 papers, 2015 to 2026). Inflammation of a joint. "A CXCR1 antagonist has been shown to decrease clinical disease scores in a murine collagen-induced arthritis model." (PMID 26103626, 2015). "In addition, CXCR1 haplotypes differed between patients with arthritis and erythema nodosum compared to controls, while CXCR2 haplotypes were significantly associated with genital and ocular involvement." (PMID 41596568, 2026). "CXCL8-based decoy proteins prevented CXCR1 and CXCR2 signaling in neutrophils and ameliorated arthritis in AIA mice." (PMID 36860872, 2023). "CXCL1 and CXCL8 induce neutrophil chemotaxis in vitro, which is also inhibited by the blockade of CXCR1/CXCR2 and DF 2162, the later inhibiting neutrophil recruitment in zymosan-induced arthritis in mice and AIA in rats." (PMID 36860872, 2023). "In spite of this, however, chondrocytes express several chemokine receptors, including CXCR1 and CXCR2 and their cognate ligands that have been extensively studied in the context of arthritis." (PMID 25135253, 2015). "Furthermore, the blockade of CXCR1 and CXCR2 (DF 2162) ameliorated arthritis by inhibiting neutrophil migration in AIA rats." (PMID 36860872, 2023).
autoimmune disease (5 papers, 2015 to 2024). A disorder resulting from loss of function or tissue destruction of an organ or multiple organs, arising from humoral or cellular immune responses of the individual to their own tissue constituents. "Overall, our study reveals CXCR1 governs DCs-mediated inflammation and autoimmune disorders and its potential as a therapeutic target for related diseases." (PMID 37709757, 2023). "Nevertheless, whether and how the CXCR1 plays critical roles in DCs-mediated inflammation and autoimmune disorders remains to be explored." (PMID 37709757, 2023). "In addition, CD56+low NK-cells also infiltrate the liver of patients with primary biliary cirrhosis, an antibody mediated autoimmune disease, following the CXCR1/IL-8 axis; curiously, hepatic infiltration by neutrophils is also found in these patients." (PMID 26543875, 2015). "Therefore, we focused on CXCR1, the first chemokine receptor cloned in 1991, and its mouse ligand CXCL5/LIX, which has been shown to mediate cell migration and granule release in neutrophils in response to bacterial infections and autoimmune diseases." (PMID 37709757, 2023).
Cirrhosis (5 papers, 2011 to 2022). A chronic disorder of the liver in which liver tissue becomes scarred and is partially replaced by regenerative nodules and fibrotic tissue resulting in loss of liver function. "Altered expression of CXCR1 in circulating monocytes of patients with cirrhosis has previously been established." (PMID 36119721, 2022). "Interestingly, monocytes/macrophages, and not neutrophils, appear to be main responders to IL-8 in liver fibrosis/cirrhosis via CXCR1." (PMID 21731723, 2011). "Interestingly, IL-8 does not seem to primarily promote neutrophil attraction during fibrogenesis, but rather contributes to accumulation of monocytes in fibrotic livers, as circulating monocytes in patients with cirrhosis significantly upregulate CXCR1 on their surface." (PMID 23259611, 2012). "In full agreement with IL-8 expression, CXCR1 mRNA levels were significantly increased in samples from CLD patients, especially in advanced fibrosis/cirrhosis and in PBC patients." (PMID 21731723, 2011). "Monocytes isolated from patients with established cirrhosis (n = 69) expressed significantly higher CXCR1 mRNA than from non-cirrhotic patients (n = 42)." (PMID 21731723, 2011).
Insulin resistance (5 papers, 2019 to 2025). Increased resistance towards insulin, that is, diminished effectiveness of insulin in reducing blood glucose levels. "A recent study assessed the effects of CXCR1/2 blockade on inflammation-induced insulin resistance in hepatocytes in vitro." (PMID 40718478, 2025). "TNF-induced insulin resistance in hepatocytes was mitigated by CXCR1/2 blockade through the inhibition of intracellular inflammatory pathways such as JNK and NF-κB and positive modulation of the metabolic profile of the cells." (PMID 40718478, 2025). "Building upon these findings, the present study aims to additional elucidate the role of CXCR1/2 signaling in IR using TNF-a induced insulin resistance in vitro models." (PMID 39627194, 2024). "By investigating the impact of CXCR1/2 inhibition on TNF-α induced insulin resistance, this study seeks to provide insights into the potential therapeutic targeting of chemokine receptors to improve insulin sensitivity." (PMID 39627194, 2024). "However, the specific contribution of the TNFα-CXCR1/2 axis to insulin resistance remains underexplored." (PMID 39627194, 2024). "Recently, in the search for new drugs to inhibit pro-inflammatory adipokine secretion in type 2 diabetes patients, emerging evidence has identified that the CXCR1/2 inhibitor ladarixin could enhance insulin resistance in 3T3-L1 adipocytes by reducing inflammation and improving insulin signaling." (PMID 38989000, 2024). "Interestingly, in our experimental conditions, CXCR1/2 inhibition in the insulin resistance model (TNF-a+LAD + INS) showed a behavior close to control (CTR + INS), thus suggesting CXCR1/2-mediated ameliorations in the pathways related to glucose uptake and insulin resistance." (PMID 39627194, 2024).